NACA2 (nascent polypeptide associated complex subunit alpha 2)
Description:
Prevents inappropriate targeting of non-secretory polypeptides to the endoplasmic reticulum (ER). Binds to nascent polypeptide chains as they emerge from the ribosome and blocks their interaction with the signal recognition particle (SRP), which normally targets nascent secretory peptides to the ER. Also reduces the inherent affinity of ribosomes for protein translocation sites in the ER membrane (M sites) (By similarity).
Synonyms: NACAL; MGC71999; ANAC
Tractability: PROTAC: UniProt records ubiquitination sites on it; ubiquitination databases record sites on it.
Gene: Protein-coding gene on chromosome 17 (61,590,421 to 61,591,219, reverse strand). Ensembl gene ENSG00000253506.
Subcellular location: Cytoplasm; Nucleus
Subcellular location (Human Protein Atlas): Cytosol
Gene Ontology:
Biological process: protein targeting to membrane
Cellular component: cytoplasm; nascent polypeptide-associated complex; nucleus
Genetic constraint (gnomAD): Loss-of-function variants: 9 observed, 15.37 expected, observed/expected ratio (o/e) 0.59, 90% interval 0.35 to 1.02. The upper end of that interval is the gene's LOEUF score, 1.02, which puts it in group 4 of 6, group 1 being the genes least tolerant of losing a copy. Missense variants: 258 observed, 265.95 expected, observed/expected ratio (o/e) 0.97, 90% interval 0.88 to 1.08. Synonymous variants: 111 observed, 104.24 expected, observed/expected ratio (o/e) 1.06, 90% interval 0.91 to 1.25.
Homologues: Orthologues: chimpanzee NACA2 (97% identical), Drosophila melanogaster gNacalpha (42% identical), Drosophila melanogaster Hmr (21% identical). Paralogues in human: NACA (90% identical), NACAD (61% identical).
Diseases named in the same sentence as NACA2 in open-access papers:
NACA2 is named in the same sentence as 4 diseases in open-access papers, as found by Europe PMC text mining. Sharing a sentence is not in itself a finding about the gene and the disease. The quoted sentences say what the papers report.
breast tumors (1 paper, 2020). "Located within the inactive TADs, five of the six aforementioned non-ATC loci (except EFCAB3) were highly methylated at shore regions of CpG island promoters (i.e., TBX2, TBX4, MRC2, and MARCH10) and non-CpG island promoter (i.e., NACA2) in 77 breast tumors compared to 10 normal controls (ref. #)." (PMID 32408897, 2020).
lung carcinoma (1 paper, 2022).
tumor (1 paper, 2017). "The expression of PA2G4P4 was also correlated with that of NACA2 in about one third of the tumor types (data not shown)." (PMID 28673244, 2017).
NACA2 also shares sentences with these, for which no sentence is quoted: bone disorder (1 paper).